TNF (tumor necrosis factor)
Diseases named in the same sentence as TNF in open-access papers (continued):
Sharing a sentence is not in itself a finding about the gene and the disease.
Insulin resistance (continued). "Increased levels of circulating LPS and TNF-a has also been reported in our previous study in UOX−/− mouse, which likely facilitate illustrate the mechanism that hyperuricemia was associated with metabolic dysfunction such as insulin resistance and atherosis." (PMID 38088975, 2023). "TNF-α plays a pivotal role in the regulation of insulin resistance and endothelial dysfunction." (PMID 37892970, 2023). "Insulin resistance (IR) was induced into primary adipocytes by using TNF alpha." (PMID 37893225, 2023). "A randomized control trial revealed that the ChE inhibitor galantamine could lower the level of TNF, a molecule that contributed to insulin resistance, and also significantly lower plasma insulin and HOMA-IR in patients with metabolic syndrome." (PMID 37138337, 2023). "Moreover, TNF-α induces insulin resistance and hyperlipidemia by activating nuclear factor-κB (NFĸB)." (PMID 37396948, 2023). "In addition, inflammatory cytokines (tumor necrosis factor-alpha and interleukin-6) released by macrophages accumulated in visceral adipose tissue can weaken insulin sensitivity and thus promote insulin resistance." (PMID 37674809, 2023). "Although the production of TNF-α may be an early event in NAFL, potentially enhancing the severity of hepatic steatosis, NAFL is strongly associated with insulin resistance (IR), which is considered a major pathogenic driver of lipid accumulation in the liver." (PMID 37407724, 2023). "TNF-α and IL-6 are considered the main inflammatory mediators of insulin resistance, which can activate various inflammatory signaling pathways, inhibit insulin signaling, and lead to insulin resistance." (PMID 36986084, 2023). "Such systemic inflammation was described as developing due to the accumulation of adipose tissue in the abdominal area, which activates macrophages, endothelial dysfunction, excessive production of tumor necrosis factor α, interleukin-6 and adipocytokines, oxidative stress, and insulin resistance." (PMID 37238705, 2023). "The putative mechanisms of sarcopenia in patients with HCC are complex and are related to chronic inflammation, including tumor necrosis factor-α and interleukin-6, insulin resistance, and low levels of vitamin D, which lead to the progression of liver fibrosis and HCC." (PMID 37895312, 2023). "Insulin resistance, abnormal metabolism of fat factors [pro-inflammatory adipokines (leptin, resistin, TNF-α), anti-inflammatory adipokine (adiponectin), specific adipokine Sfrp5], and vitamin D deficiency are all possible causes of abnormal blood lipids in visceral obese individuals." (PMID 37674809, 2023). "Overexpression of TNF-α presented in OSA may additionally enhance DM development by suppressing GLUT-4 expression and promoting insulin resistance through TNF-α/IKKβ/IKβ/NF-κB signaling pathway." (PMID 37547923, 2023). "In addition, excessive body fat promotes the secretion of interleukin (IL) and tumor necrosis factor alpha (TNFα), thereby increasing the inflammatory response, inhibiting insulin signal transduction, and inducing insulin resistance." (PMID 35889886, 2022). "Moreover, punicic acid (5, 10, and 30 μM) significantly attenuated the levels of IL‐6, IL‐1β, and IFN‐γ following the TNF‐α‐induced insulin resistance in three T3‐L1 adipocyte cells." (PMID 36541264, 2022). "Taken together, inflammation induced by pro-inflammatory cytokines such as IL-6 and TNF-α is inversely correlated with insulin signaling where it might lead to insulin resistance." (PMID 36504710, 2022). "Stevia also could lower the interleukin‐6 (IL‐6), IL‐1, and TNF‐α and thus could help in lowering insulin resistance in patients with diabetes." (PMID 36171777, 2022). "Any abnormal change in pro-inflammatory cytokines (IL-6 and TNF-α) could diminish insulin sensitivity and contribute to insulin resistance." (PMID 36014565, 2022).
Insulin resistance (continued). "Aβ was further shown to potentiate the TNF-α/PICR-dependent activation of PKR, another IRS-1 Ser-kinase in neurons, to drive IRS-1 phosphorylation and insulin resistance as well as ER stress-associated eIF2α induction and subsequent synaptic damage, LTP impairment and memory deficits in vivo." (PMID 36117625, 2022). "Further research has begun to uncover a mechanism for TNFα’s role in insulin resistance." (PMID 36078455, 2022). "In addition, IL-6 is one of the adipokines that promotes insulin resistance and dyslipidemia in humans, and TNF-α is the driver behind dyslipidemia." (PMID 35872979, 2022). "Grape powder extract (rich in quercetin-3-glucoside, catechin, epicatechin, rutin, gallic acid and resveratrol) showed to decrease LPS-stimulated inflammation in macrophages by affecting the gene expression of IL-6, IL-8, IL-1β and TNF-α, and in turn decreased insulin resistance." (PMID 35057523, 2022). "Patients with insulin resistance, prediabetes, and diabetes have activation of tumor necrosis factor-α resulting in inhibition of phosphorylation of the tyrosine kinase enzyme in insulin receptors in the periphery, and this is one of the main mechanisms of peripheral insulin resistance." (PMID 35897033, 2022). "Additionally, LPSs also triggers pro-inflammatory cytokines including tumor necrosis factor alpha (TNF-α) which plays a crucial role in insulin resistance and inflammatory cell uptake in patients with non-alcoholic fatty liver disease." (PMID 35910609, 2022). "Inflammatory cytokines such as TNFα also reduce insulin function and facilitate insulin resistance." (PMID 35462993, 2022). "Conversely, mice lacking TNFα due to targeted mutation are protected from obesity-induced insulin resistance." (PMID 36551210, 2022). "TNFα is another cytokine produced within the adipose tissue, mainly from the local macrophages, and its production also varies proportionally with adipose tissue mass and correlates with insulin resistance, both being major features of MetS." (PMID 35054972, 2022). "In addition, adiponectin, which negatively correlates with BMI, counteracts insulin resistance and exerts anti-inflammatory effects by inhibiting the expression of IL-6 or tumor necrosis factor alpha (TNFα)." (PMID 35323701, 2022). "These high cortisol levels due to stress may elevate biomarkers such as blood glucose, TNF-α and insulin resistance." (PMID 35252372, 2022). "It has been suggested that TNF-a might be involved in the development of insulin resistance, inflammation and fibrosis in patients with NASH, therefore, anti-TNF medication may present a potential therapeutic target in patients with NASH." (PMID 35204498, 2022). "In contrast, plasma TNF-α levels were positively and significantly correlated to insulin resistance and visceral adiposity expressed by waist circumference in both SS groups, but more markedly in Black participants (r = +0.77, r = +0.86, p < 0.001, respectively)." (PMID 35684085, 2022). "TNF-α has been shown to promote insulin resistance in different ways." (PMID 36145106, 2022). "For example, the pro-inflammatory cytokine tumour necrosis factor α (TNFα) promotes insulin resistance in adipocytes which leads to development of diabetes type 2 and an increased risk for diabetes type 2 promotes cardiovascular neurodegenerative, cancer and autoimmune diseases." (PMID 35328666, 2022). "For example, TNF-α, a cytokine that is known to promote cachexia and is produced by macrophages and adipocytes, and IL-6, which has marked catabolic function, are also involved in insulin resistance in type II diabetic patients." (PMID 34980115, 2022). "Chronic inflammation and insulin resistance are the main characteristics of diabetes and could be induced by LPS or TNFα in vitro or in animal models." (PMID 35955706, 2022).
Insulin resistance (continued). "In addition, TNF-α has been reported to induce apoptosis and autophagy of C2C12 cells by activating NF-κB signaling, while knockdown TNF reduces insulin resistance in C2C12 cells." (PMID 35464065, 2022). "A proinflammatory diet might contribute to the risk of T2D by elevating circulating levels of inflammatory cytokines (e.g., interferon γ, IL-1, IL-6, IL-8, CRP, and TNF-α), which can lead to insulin resistance." (PMID 35685508, 2022). "Not only that, but TNF-α was also reported to modify the permeability of the intestinal capillaries, which could hamper the metabolic action of insulin, further aggravating insulin resistance." (PMID 35887957, 2022). "In peripheral insulin resistance, TNF-α and JNK signaling activation is an important mechanism." (PMID 36143409, 2022). "Moreover, insulin resistance, hepatitis C, pancreatic cancer, TNF signaling pathway, insulin signaling pathway, and PI3K-AKT signaling pathway were the mechanisms by which apple pollen exerted its therapeutic effect on T2DM." (PMID 35656465, 2022). "The anti-inflammatoryproperties of adiponectin may play a central role in slowing the progression ofatherosclerosis in T2DM and may have a beneficial effect on insulin resistance byinhibiting TNF-alpha-induced activation of NF-κB in endothelial cells." (PMID 39077619, 2022). "Kupffer cells incubated with bovine serum albumin (BSA)-palmitate for 24 h expressed higher levels of the pro-inflammatory cytokines IL-6, TNFα and IL-1β, all of which are known to induce insulin resistance, than Kupffer cells incubated with BSA-oleate or BSA-control." (PMID 35955975, 2022). "In an animal study by Hosokawa, Miyashita, Nishikawa, Emi, Tsukui, Beppu, Okada and Miyashita, dietary fucoxanthin inhibited the expression levels of pro-inflammatory adipocytokines mRNA (TNF-α and MCP-1) associated to insulin resistance, resulting in over-inflammation of the liver." (PMID 35954003, 2022). "Furthermore, within the pancreatic islets, the production of TNF by macrophages can promote a dysfunction of the beta cells and can directly lead to insulin resistance." (PMID 36648872, 2022). "In type 2 DM and hepatogenous DM, insulin resistance is common, and the insulin level increases, boosting the formation of oxygen free radicals and stimulating the release of inflammatory mediators including tumor necrosis factor-α (TNF-α)." (PMID 35345832, 2022). "Considering the evidence for the role of cytokine TNFα in insulin resistance in obese models, it might be possible that the elevated TNFα levels found following sleep deprivation contributes to insulin resistance in the same way." (PMID 36078455, 2022). "Further reports also indicate that elevated TNF-α can directly modify the functioning of ß-cells by provoking their apoptosis, leading to the disintegration and decline of working ß-cells and, therefore, inducing insulin resistance." (PMID 35887957, 2022). "However, the reverse—such as the increase in the production of FFAs and triglycerides—occurs when TNF-α is administered, which validates the role of TNF-α in the pathophysiology of insulin resistance." (PMID 35887957, 2022). "TNF production and reduced mitochondrial gene expression could be factors of regional insulin resistance, which would inhibit angiogenesis, reorganization of elastic fibers, and wound healing during the aging process reported by previous studies." (PMID 35001792, 2022). "The observed significant increase in the levels of TNFα in adipose tissue of infected RD adult mice may induce a proinflammatory status that could contribute to the development of systemic insulin resistance." (PMID 35329973, 2022). "Cytokines and TNF-α remain upregulated after remission of Covid-19, which may induce beta cell dysfunction and insulin resistance." (PMID 35292829, 2022). "Consequently, a pathway for the development of insulin resistance due to oxidative stress via TNF-α-induced ceramide accumulation can be inferred from this analysis." (PMID 36292583, 2022).
Insulin resistance (continued). "Furthermore, IL-6 and TNF-α enhance the survival of inflammatory factors such as resistin, reinforcing insulin resistance." (PMID 36355818, 2022). "The major role of IL-1β and TNF-α in particular insulin resistance has been shown repeatedly." (PMID 35455066, 2022). "In adipocytes, TNFα induces insulin resistance and upregulates lipolysis." (PMID 35557517, 2022). "Substances such as TNF-α might induce insulin resistance and increase systolic blood pressure by generating hydrogen peroxide." (PMID 35888020, 2022). "The results in addition showed insulin resistance, hyperinsulinemia, hyperandrogenism and oxidative stress as well as a significant increase in inflammatory biomarkers (NF-kB/TNF- and IL-6), with a significant decrease in TG, TC, FFA, GSH and G6PD in the adipose tissue of PCOS animals." (PMID 36071485, 2022). "Other data suggest that IL-6 may be in-volved in inflammation and insulin resistance, while TNF-α may induce the progression of NAFLD and promote the development of steatohepatitis." (PMID 36432495, 2022). "With the induction of lipopolysaccharide and saturated fatty acid, M1 macrophages can activate and secrete tumor necrosis factor α (TNF-α), interleukin-6 (IL-6), interleukin-12 (IL-12), interleukin-1β (IL-1β) and other pro-inflammatory factors, leading to inflammation and insulin resistance." (PMID 35757707, 2022). "A recent study demonstrated that insulin resistance induced by TNF-α in 3T3-L1 adipocytes was restored by rosiglitazone, an agonist of the peroxisome proliferator-activated receptor (PPAR) γ2 (PPARG2), an important nuclear receptor for adipocyte differentiation." (PMID 35028437, 2022). "The KEGG analysis results showed that targets of YXQNW enriched in some AD-related pathway such as the “PI3K-Akt signaling pathway” (p = 3.48E-16), “insulin resistance” (p = 7.12E-16), and “TNF signaling pathway” (p = 4.20E-15), which have been reported to be associated with AD by different groups." (PMID 36105078, 2022). "ACC phosphorylation was decreased in palmitate-induced and TNF-induced insulin resistance." (PMID 35055191, 2022). "This may be associated with placental secretion of insulin-like growth factor, adipokines, tumor necrosis factor-α, cytokines and insulin resistance." (PMID 36615730, 2022). "TNF-α can decrease adiponectin secretion, which could explain lower levels of adiponectin in patients with psoriasis and consequent insulin resistance." (PMID 35743091, 2022). "On the other hand, the downregulated genes were enriched in insulin resistance (23 genes), TNF signaling pathway (20 genes), serine, glycine, and threonine metabolism (12 genes), glyoxylate and dicarboxylate metabolism (10 genes), and starch and sucrose metabolism (9 genes) (p < 0.05)." (PMID 36176772, 2022). "TNF-α develops insulin resistance, whereas adiponectin improves insulin sensitivity." (PMID 35010830, 2022). "Insulin resistance in obese patients can be explained due to the inflammatory response with alteration of substances that act systemically, participating in several metabolic processes, such as leptin, adiponectin, and TNF-α, which play a fundamental role in insulin resistance." (PMID 35703718, 2022). "The possible mechanism of the relationship between VAI and insulin resistance is as follows:Visceral adipocytes secrete adipose-specific cytokines, such as leptin and adiponectin, as well as inflammatory cytokines (tumor necrosis factor-α and interleukin 6), which increase IR." (PMID 35937809, 2022). "High levels of the inflammatory mediator, such as TNF-α, might contribute to an increase in insulin resistance." (PMID 35016229, 2022). "Visfatin, an adipokine present mainly in visceral adipose tissue, which induces the production of IL-6, IL-1β, and TNF-α, has a crucial inflammatory impact on the liver and maybe also related to insulin resistance." (PMID 35052633, 2022).
Insulin resistance (continued). "Elevated concentrations of TNF-α, IL-1b, IL-6 and leptin may also worsen insulin resistance and increase fetal overgrowth." (PMID 35957820, 2022). "In addition to the JNK signaling pathway, insulin resistance is also closely related to NF-κB activation, which is induced by TNF-α." (PMID 36230963, 2022). "Thus, it can reduce fasting blood glucose and insulin resistance and reduce inflammation by decreasing serum levels of IL-6, TNF-α, and resistin and increasing serum levels of adiponectin and irisin, which ultimately improve insulin sensitivity." (PMID 36355818, 2022). "Moreover, pro-inflammatory cytokines such as TNF-α and IL-6 interfere with the insulin signaling pathway and increase insulin resistance under stress conditions." (PMID 36079032, 2022). "TNF-α promotes insulin resistance and inflammation of blood vessels." (PMID 35382771, 2022). "Moreover, TNF also promoted insulin resistance and ultimately led to increased hepatic steatosis in patients with NAFLD." (PMID 35422858, 2022). "In addition, TNF-α plays an important role in altering carbohydrate and lipid metabolism and insulin resistance, which has been identified as essential contributors in cancer cachexia metabolism." (PMID 35159388, 2022). "Since TNF-α could induce insulin resistance, the effect of fermented SS on glucose uptake was investigated in TNF-α-induced FL83B cells in the presence of insulin." (PMID 35893262, 2022). "The proinflammatory M1 macrophages are capable to secrete TNF-α and IL-6 which may lead to insulin resistance and CXCL16 upregulation." (PMID 35784287, 2022). "However, there are various other inflammatory cytokines, such as IL-6, which are related to insulin resistance apart from TNF-α." (PMID 34997408, 2022). "Notably, TNF-α has been previously recognized as the most prominent factor contributing to insulin resistance in both diabetes and diabetes pregnancy." (PMID 35317005, 2022). "However, an extract rich in extract chalcones also decreases the TNF-α levels and in turn reduces insulin resistance." (PMID 36501129, 2022). "In addition to inducing insulin resistance in insulin-responsive tissues, TNF-α also plays an important role in the pathogenesis of β cell dysfunction." (PMID 35198097, 2022). "Cell models for insulin resistance such as dexamethasone- and TNF-α-treated adipocytes revealed that ROS overproduction may be a key trait of insulin resistance." (PMID 36246880, 2022). "This appeared to be due to TNFα-mediated induction of the anti-inflammatory CEACAM1-4L variant in M2 macrophages associated with white adipose tissue to enhance innate immunity and counter inflammation-driven insulin resistance." (PMID 35457157, 2022). "In addition, TNF-α plays a central role in the pathogenesis of insulin resistance, T2D, and various CIRDs such as RA, PsA, and AS." (PMID 35629988, 2022). "TNF-α phosphorylates Serine307 of IRS-1(insulin receptor substrate 1) by activating downstream c-Jun NH2-terminal kinase (JNK), impairing glucose uptake and causing insulin resistance in adipose tissue." (PMID 36496995, 2022). "Moreover, TNF-α was positively correlated with HbA1c and insulin resistance, measured by the Homeostatic Model Assessment for Insulin Resistance index, in subjects with DM." (PMID 36362984, 2022). "TNF production by macrophages recruited from the periphery is central to insulin resistance." (PMID 34837070, 2022). "Similarly, elevated levels of TNF-α can disrupt insulin signalling through serine phosphorylation, thereby inducing insulin resistance in adipocytes and surrounding tissues and leading to the development of T2DM28." (PMID 36376474, 2022). "Notably, a positive correlation between TNFα levels and the development of insulin resistance has been previous reported in obese individuals." (PMID 35586621, 2022).